MCL1 (MCL1 apoptosis regulator, BCL2 family member)
Diseases named in the same sentence as MCL1 in open-access papers (continued):
Sharing a sentence is not in itself a finding about the gene and the disease.
cancer (continued). "Taken together, our data indicate that enhancement of ubiquitination-dependent Mcl-1 turnover might be a promising approach for cancer treatment." (PMID 32081857, 2020). "Due to the recognized relevance of this family in cancer progression and response to therapy, different efforts have made in recent years in order to develop small molecules able to target anti-apoptotic proteins such as Bcl-2, Bcl-xL and Mcl-1." (PMID 32455818, 2020). "Similarly, the apoptosis-related gene MCL1 and collagen genes involved in metastasis are also targeted by this family in cancer." (PMID 32117755, 2020). "Interestingly, STAT3 has been implicated in cancer cell survival by regulating the transcription of other anti-apoptotic members of the Bcl-2 family, such as BCL2, Bcl-xL, and MCL1." (PMID 33396645, 2020). "Emerging studies have revealed the crucial role of MCL1 in the chemoresistance of cancer cells." (PMID 32699213, 2020). "Indeed, cancer patients with high levels of MCL1 expression have been shown to encounter drug resistance, relapse and poor prognosis outlook." (PMID 32699213, 2020). "This suggests that NOXA induction could be an effective means to antagonize MCL1 activity in cancer." (PMID 32824203, 2020). "However, functional redundancy and compensatory roles among the antiapoptotic BCL-2-like proteins can establish “codependencies” (e.g. BCL-XL/MCL-1) that hamper efficient cancer cell elimination when a single BCL-2-like protein is targeted." (PMID 32312973, 2020). "Furthermore, genetic and pharmacologic targeting of MCL1 or BCL2L1 has been shown to effectively improve the sensitivity of cancer cells to radiotherapy." (PMID 32404045, 2020). "MCL-1 belongs to the Bcl-2 family and regulates apoptosis in normal and cancer cells." (PMID 32907612, 2020). "Thus, ectopic expression of BCL2L1 rescues cancer cells from transcriptional repressor treatment and tumors with high levels of BCL2L1 or loss of BAK are resistant to MCL1 depletion." (PMID 32645016, 2020). "In this review, we summarize the major functions of MCL-1 with a special focus on cancer, provide insights into its different roles in solid vs. hematological tumors and give an update about the (pre)clinical development program of state-of-the-art MCL-1 targeting compounds." (PMID 33308268, 2020). "Similarly, previous studies have shown that ABT-263 upregulates MCL1 expression in cancer cells, while A-1210477 increases MCL1 accumulation, due to the inhibition of NOXA-mediated MCL1 degradation." (PMID 32486166, 2020). "Because MCL1 has been shown to be both an intrinsic and acquired resistance factor that limits the efficacy of various antitumor agents for different cancers, this highlights the need to employ effective MCL1 inhibitors that can be used either as a single agent or in combination regimens." (PMID 32527042, 2020). "In addition, Mcl-1 is overexpressed in various types of cancer, which is related to the evasion of cell death and acquisition of resistance to chemotherapeutic drugs." (PMID 32863764, 2020). "Given its potential role in resistance to radiation, the CDC20/Mcl-1/p-Chk1 pathway might be a promising target to overcome radioresistance and increase the efficacy of cancer therapy." (PMID 32932732, 2020). "However, so far, there were no Mcl-1 inhibitors have been approved successfully, and the development of alternative approaches to target Mcl-1 is still an urgent demand for cancer treatment." (PMID 32081857, 2020). "Only two of them (TM-(–)-18 and TM-(–)-4a) exerted anti-cancer activities with the loss of Mcl-1 and partly reduced Bcl-2, while the other analogues had no such effects." (PMID 32260280, 2020). "MCL-1 is another attractive therapeutic target as it is highly expressed in human cancers." (PMID 31973201, 2020).
cancer (continued). "IHT is an attractive candidate to develop as an anti-cancer drug due to its decrease in expression of Bcl-2, Mcl-1, XIAP, and Survivin in NCI-H460 tumorspheroids and its downregulation of Mcl-1 and Survivin in A549 with siNR4A1 to activate the intrinsic apoptosis pathway." (PMID 33172112, 2020). "Thus, novel therapeutic strategies are urgently needed to target Mcl-1 and sensitize the anti-cancer activities of Bcl-2 inhibitors for effective treatment of NSCLC." (PMID 32587776, 2020). "For GI cancer, EGFR, PDGFRA, VEGFA, PDPK1, and MCL1, etc. could be validated as drug targets for anti-cancer drugs." (PMID 32523951, 2020). "MCL-1 is a central driver of drug resistance against a plethora of established cancer treatments." (PMID 33308268, 2020). "Downregulation of Mcl-1 transcription by inhibiting STAT3 cascade may be a potential strategy for the treatment of this cancer." (PMID 31956373, 2020). "Identification of additional deubiquitinases that regulate MCL-1 protein stability may offer alternative targets for cancer prevention and treatment." (PMID 32802178, 2020). "MCL1 is one of the most highly amplified genes in human cancers." (PMID 32131385, 2020). "Moreover, an overexpression of MCL-1 is observed in many human cancer cells and MCL-1 is therefore considered a possible target in cancer therapy." (PMID 33019591, 2020). "Previously, many different strategies were used to indirectly inhibit MCL1 to treat cancer." (PMID 32152266, 2020). "To understand whether the other cancer-related genes identified on amplicon 1q21 may play a role in the sensitivity to the MCL-1 inhibitor, we analysed their expression in the cell line cohort." (PMID 32913197, 2020). "Given the anti-apoptotic property of MCL-1, MCL-1 has been shown to be both an intrinsic and acquired resistance factor that impairs the potency of various antitumor agents, and studies have suggested the utility of cancer therapy targeting MCL-1 based on the anti-apoptotic property of MCL-1." (PMID 32586376, 2020). "Mcl-1 is a potent antiapoptotic protein and amplifies frequently in many human cancer." (PMID 31432325, 2020). "Besides, some agents, synergistically promoting the degradation of MCL1, have been reported to induce apoptosis in many types of cancer cells." (PMID 33126914, 2020). "Previous studies have shown that DHA induces apoptosis, autophagy and ferroptosis of cancer cells via caspase activation, cytochrome c release, Mcl-1 down-regulation, MEK/ERK inactivation, JNK/NF-κB pathway activation, AKT-mTOR pathway suppression, and autophagy-dependent degradation of ferritin." (PMID 32431605, 2020). "Mcl-1 is an important anti-apoptotic protein in the Bcl-2 protein family, which can help tumor cells "evade" the drug attack and continue to grow so that tumor cells can survive, leading to the resistance of cancer patients to the chemotherapeutics." (PMID 32231716, 2020). "However, MCL-1 stands out as it is one of the most frequently and highly amplified genes in human cancers." (PMID 33308268, 2020). "Finally, the ability of CDK9 to maintain increased levels of the anti-apoptotic protein MCL1 is considered one of the mechanisms that leads to cancer cell survival and subsequent hematological and solid tumors development." (PMID 32903585, 2020). "Additionally, evidence has suggested that, in NSCLC, Mcl-1 inhibition showed superior potential for having a cancer therapeutic effect when compared with Bcl-xl inhibition." (PMID 32260280, 2020). "In line with previous reports in alternative cancer cohorts, genomic gains of MCL-1 occurred at higher frequency than any other BCL-2 family member and did not cause compensatory deregulation of other BCL-2 protein family members, as detected in the TCGA and TRACERx datasets." (PMID 32913197, 2020). "To understand whether MCL-1 is differentially expressed in cancer vs healthy tissue, we analysed MCL-1 protein levels in 11 primary LUAD patient samples and matched healthy lung tissue." (PMID 32913197, 2020).
cancer (continued). "However, as a therapeutic target of cancer, the relationship between MCL-1 and CSC is poorly explored." (PMID 32586376, 2020). "The observation that targeted inhibitors of the MAPK pathway induce MCL-1 dependence suggests that prior treatment of cancer cells with MAPK pathway inhibitors might promote sensitivity to MCL-1 inhibitors." (PMID 31727958, 2019). "We further validate that splicing modulator induces selective apoptosis in cancer cell lines with endogenous amplification and high expression of MCL1 or BCL2A1, and combination of splicing inhibition and BCLxL (encoded by BCL2L1) inhibition induces a synergistic cytotoxicity in cancer cells." (PMID 30635584, 2019). "Given that the expression of Bcl-xl and Mcl-1 was stringently maintained by BRD4 in other cancer cells, we assumed that BETd-260 might also impact the expression of these two anti-apoptotic Bcl-2 family members in OS cells." (PMID 31653826, 2019). "As a well‐known tumor suppressor, miR‐101 has multiple targets, including Fos, EZH2, Cox‐2, N‐myc, and Mcl‐1, that play roles in cancers 29, 30, 32, 33, 34, 35, indicating that the activity of miR‐101 is performed through various mechanisms by targeting different genes." (PMID 30984544, 2019). "Abundant evidence to suggests that Mcl-1 is an important cancer target." (PMID 30738430, 2019). "Overexpression of anti-apoptotic proteins MCL1 and Bcl-xL are frequently observed in many cancers." (PMID 31294695, 2019). "Mcl-1 inhibitor alone, or in combination with other inhibitors of key molecules presents a promising novel strategy to trigger cell death pathways in the treatment of cancer therapy." (PMID 31601252, 2019). "Interestingly, later studies indicated that YM155 is able to inhibit Mcl-1 expression in PC-3 (prostate), H28 (mesothelioma), U251 and D37 (glioblastoma) cancer cells." (PMID 31439015, 2019). "To date, small-molecule Mcl-1 inhibitors are emerging for cancer treatment." (PMID 31076590, 2019). "Under these conditions, U0126 addition reduced MCL-1 protein levels in cancer cells." (PMID 30631150, 2019). "Furthermore, AKT activation contributes to evasion of apoptosis through inducing anti-apoptotic proteins such as C-FLIP, XIAP, and MCL-1 inhibited apoptotic signaling transduction in cancer cells." (PMID 31905887, 2019). "Downregulation of Mcl-1 expression in tumor cells has been shown to increases the cancer cell sensitivity to drug treatments, suggesting that Mcl-1 may play a critical role in cellular viability." (PMID 31171771, 2019). "Also, these findings are supported by reports in other cancers suggesting that cancer cells often use rapid Mcl-1 translation to evade therapeutically-induced tumor cell death." (PMID 31595181, 2019). "As Mcl-1 is known to be critical for cancer cell survival, this result implies that the principal mechanism of action of RT may involve the targeting of the Mcl-1 function." (PMID 31117253, 2019). "A recent study revealed that VLCAD interacts with the BH3 domain of MCL-1 via a non-canonical mechanism, which is associated with chemoresistance in human cancer and merits further study." (PMID 31892336, 2019). "Therefore, developing a highly potent and selective small-molecule inhibitor of the pro-survival protein MCL1 will provide a suitable therapeutic scheme for cancer patients." (PMID 31467488, 2019). "Thus MCL-1 inhibition efficiently prevents the protective cross-talk between bCAFs and cancer cells." (PMID 30631150, 2019). "Combinations of S63845 or A1331852 with other anti-cancer agents that downregulate BCL-XL or MCl-1 respectively in tumor vs. normal cells could also be effective." (PMID 31019203, 2019). "Mcl-1 is an important cancer target for drug therapy, through which normal apoptosis may be restored by inhibiting its protective function." (PMID 31692474, 2019). "We confirmed that MCL-1 expression in cancer cells was induced under these conditions (left)." (PMID 30631150, 2019).
cancer (continued). "Therefore, compounds with potent activity in eliminating Mcl-1 in cancer cells are of interest as good candidates for Mcl-1-targeted therapy." (PMID 31117253, 2019). "Several studies investigating the role that MCL-1 expression plays in cancer development and treatment have resulted in significant efforts to develop compounds, such as alvocidib, that may target this apoptosis-inhibitory protein." (PMID 30815228, 2019). "Mcl-1 belongs to Bcl-2 family which considered an important player in regulation of apoptosis and any change in their expression levels will lead to the progression of human cancer." (PMID 31870103, 2019). "Interestingly, our results demonstrated that KP markedly reduced EGF-induced Mcl-1 production in HeLa cells, confirming its anti-cancer ability to modulate the EGFR/MAPK signaling cascade." (PMID 31470515, 2019). "So, one important question is whether other proteins in cancer cells could be drugged, together with MCL1, to overcome or even avoid this resistance." (PMID 31294695, 2019). "Apoptosis in KPT-330-sensitive cancer cells depends on Mcl-1 reduction." (PMID 31113936, 2019). "The sensitivity of cancer cells to BH3 mimetics is highly dependent on the protein level of MCL1." (PMID 31467488, 2019). "Thus, anti-apoptotic members of the Bcl-2 family, including Bcl-2, Bcl-XL, Bcl-w, and Mcl-1, support the invasion and metastasis in various types of cancer." (PMID 31921862, 2019). "S63845, a small molecule that specifically binds with high affinity to the BH3-binding groove of MCL1, exerts anti-tumor activity in MCL1-dependent cancer cells in vitro and in vivo, while sparing normal tissues at efficacious doses, which represents a potential breakthrough in cancer therapy." (PMID 30139386, 2018). "It appears conceivable that up-regulation of miR-576-5p might rescue the cancer cell from apoptosis, e.g. by up-regulation of MCL1 and BCL9, thereby increasing its invasive phenotype." (PMID 30197759, 2018). "Furthermore, encouraging preclinical studies of BH3 mimetics that target other BCL-2 pro-survival members, particularly MCL-1, offer promise for cancers resistant to venetoclax." (PMID 29099483, 2018). "Notably, in some cancers, translation of MCL-1 is cap-dependent, which means inhibition of mTOR would suppress MCL-1 by blocking cap-dependent translation." (PMID 29374168, 2018). "This oncogenic role for MCL-1 may be widespread as the MCL1 locus is one of the most frequently amplified regions of the human genome across a wide variety of cancers including breast cancer." (PMID 29339815, 2018). "Therefore, our data demonstrate that USP13 is a novel regulator of MCL1 stability and a potential therapeutic target for cancer treatment." (PMID 29335437, 2018). "In addition to miR-29 and miR-101, several other miRNAs have been validated to target MCL1 in multiple cancer types in the past decade." (PMID 29361709, 2018). "Cancer researchers have long sought an effective MCL-1 inhibitor." (PMID 29099483, 2018). "Recently, researchers investigated miR101/MCL1 signaling in other cancers." (PMID 29484127, 2018). "Thus, combining the two treatments to inhibit MCL‐1 together with BCL‐2/BCL‐XL should effectively induce apoptosis in cancer cells." (PMID 29352505, 2018). "On the other hand, USP13 displays increased activity in human cancers and may represent a more titratable and episodic strategy for MCL1 inhibition to selectively kill tumor cells." (PMID 29335437, 2018). "However, although CLL is an example of a disease quite homogeneously dependent on BCL-2, a cancer homogeneously dependent on MCL-1 has yet to be identified." (PMID 29077093, 2018). "Interestingly, a number of recent studies have shown that inhibition of Mcl-1 expression sensitizes cancer cells to cisplatin-induced apoptosis." (PMID 30445944, 2018). "Mcl-1 amplification is a common genetic abnormality observed in human cancer." (PMID 30086763, 2018).
cancer (continued). "Similarly, somatic copy number amplification of both the MCL1 and BCLxL genes have been detected across human cancers." (PMID 29361709, 2018). "Therefore CDK9 inhibition prevents productive transcription and is associated with a global reduction in mRNA, including genes, such as MYC and MCL-1, which regulate proliferation and survival of cancer cells." (PMID 29471852, 2018). "However, ABT-199 shows limited efficacy in most cancers due to the functional redundancy of Bcl-2, Bcl-xL, and Mcl-1 in anti-apoptosis." (PMID 29520102, 2018). "Indeed, several studies have shown that targeting Mcl-1 by either chemical agents or genetic approaches resulted in a significant enhanced anti-cancer activity of ABT-737 in both in vitro and in vivo models." (PMID 29543705, 2018). "Although an increase in MCL1 expression plays an important role during cell differentiation and MCL1 is known to be overexpressed in multiple cancer types, the expression profile of the other two splicing variants (MCL1S and MCL1ES) in vivo has been largely ignored." (PMID 29361709, 2018). "In addition, these cytokines promote the expression of c-Flip, Bcl-xL, and Mcl-1, which are related to apoptosis, and additionally facilitate cancer cells growth." (PMID 30643796, 2018). "Combining BH3 mimetics with mimics of these microRNAs may be a promising therapeutic option for cancers displaying MCL-1-mediated resistance." (PMID 29570632, 2018). "As the regulation of VDAC1 by Mcl-1 also stimulates cancer cell migration, Mcl-1 inhibitors may not only be useful to eliminate Mcl-1-dependent cancers by provoking cell death but also by counteracting metastasis." (PMID 28516063, 2017). "MCL1 is, therefore, regarded as a potential target for cancer therapy." (PMID 29072681, 2017). "FBXW7, which is regulated by miR-223, has been identified as a tumor suppressor gene in several cancers, and plays key roles in modulating the degradation of various onco-protein substrates, including c-Myc, cyclinE, Notch, c-Jun, mTOR, and MCL1." (PMID 28507201, 2017). "In addition, MCL1 was involved in proliferation, apoptosis and metastasis of several cancer cell lines." (PMID 28881590, 2017). "In addition, increased levels of Bcl-2 or Mcl-1 promote accumulation of apoptotic resistant neoplastic cells and also help cancer cells evade immune-surveillance." (PMID 29156771, 2017). "Interestingly, in addition to genetic tools, our results showed that pharmacological mTOR and/or Mcl-1 inhibition using rapamycin and sorafenib respectively sensitized cancer cells to primarily tolerated doses of sunitinib." (PMID 29066973, 2017). "In addition, it has been reported that miR-125b was able to promote apoptosis in various cancer cell lines by direct or indirect targeting of MCL1." (PMID 28881590, 2017). "Therefore, small-molecule inhibitors of Mcl-1 can be useful as potential therapeutic agents for cancer treatments." (PMID 28903337, 2017). "Importantly, increased mTORC1 activity and Mcl-1 level represented a pro-survival cellular response to the mild to moderate stress triggered by these sunitinib doses since inhibiting mTORC1 or depleting Mcl-1 sensitized cancer cells to tolerated doses." (PMID 29066973, 2017). "MCL-1 was demonstrated to be an essential and universal target of cardiac glycosides, and cardiac glycosides cause a downregulation of the MCL-1 protein in various human adherent and non-adherent cancer cells." (PMID 28706279, 2017). "Taken together, our results suggest that fine tuning of the levels of pro-apoptotic protein BOK and anti-apoptotic protein Mcl-1 may decide the fate of cancer cells to either undergo apoptosis or proliferation." (PMID 29156771, 2017). "Moreover, the inability of ABT-737 to target Mcl-1 and the enhancement of Mcl-1 expression conferred resistance in cancer cells." (PMID 27935869, 2017).